LCN2 (lipocalin 2)
Diseases named in the same sentence as LCN2 in open-access papers (continued):
Sharing a sentence is not in itself a finding about the gene and the disease.
Insulin resistance (continued). "Moreover, in another study analyzing adult patients with NAFLD, urinary LCN2 levels correlated well with the body mass index, insulin resistance, and lipid profiles." (PMID 27729871, 2016). "Moreover, circulating lipocalin-2 concentration was positively correlated with insulin resistance index and inflammatory markers." (PMID 22292925, 2012). "Lipocalin-2 is a novel adipokine with connection to insulin resistance." (PMID 22292925, 2012). "However, evidence from large-scale populations about the relationship between lipocalin-2 and glucose metabolism, insulin resistance and chronic low-grade systemic inflammation is scarce." (PMID 22292925, 2012). "Furthermore, plasma lipocalin 2 levels are positively correlated with BMI, adiposity, hyperglycemia, and insulin resistance." (PMID 21423737, 2011). "The association between the increase in LCN2 concentrations and the development and severity of T2D can be explained through the evidence that demonstrates that LCN2 stimulates the increase of TNF-a and IL-6, cytokines that have been widely recognized as inducers of insulin resistance." (PMID 39808380, 2025). "In addition, LCN2 can stimulate the mRNA and protein expression of peroxisome proliferator‐activated receptor gamma and adiponectin in adipocytes, which is known to alleviate insulin resistance." (PMID 38035773, 2024). "In individuals with excessive body fat mass, lipocalin-2 is an inflammatory marker produced by adipocytes and being so as a mediator for chronic low-grade inflammation, which subsequently disturbs insulin signaling and contributes to the development of insulin resistance and type 2 diabetes." (PMID 37238398, 2023). "Hence, the accumulated visceral fat might account for the serum lipocalin-2 elevation during insulin resistance." (PMID 22292925, 2012). "These cytokines upregulated EGR1 expression in hepatocytes, adipocytes and skeletal myocytes to transcriptionally activate its downstream targets LCN2 and SOCS3, thus aggravating insulin resistance in SH." (PMID 40523992, 2025). "LCN2 activates the NLRP3 axis, sustaining adipose inflammation, impairing mitochondrial glucose handling, and contributing to insulin resistance." (PMID 41303567, 2025). "In this study, we analysed serum levels of RBP4, LCN2 and hsCRP in patients diagnosed with IFG, IGTand T2DM and a control group and their relationships with other variables of insulin resistance, carbohydrate metabolism and homeostasis." (PMID 40951890, 2025). "In summary, LCN2 and RBP4 exert similar effects in insulin resistance and glucose metabolism, while LCN13 and MUP1 on the other hand exert opposite effects." (PMID 38673873, 2024). "The second correlation was found between lipocalin-2 and TNF-α, a predictor of insulin resistance in human pregnancy." (PMID 34769010, 2021). "Bone-derived osteocalcin (OCN) and lipocalin-2 (LCN2) regulate glucose metabolism and improve insulin resistance." (PMID 31920965, 2019). "Here, we examined the relationships between adiposity and insulin resistance and circulating levels of adiponectin, FABP4, lipocalin-2, PAI-1 and FGF21 before and after high fat overfeeding for 28 days." (PMID 24205333, 2013). "Mechanistically, increased TSH levels in subclinical hypothyroidism promoted the secretion of cytokines IL-1α, IL-1β and IL-6 by inducing macrophage M1 polarization, which upregulated EGR1 to transcriptionally activate LCN2 and SOCS3 in insulin target cells, thereby exacerbating insulin resistance." (PMID 40523992, 2025). "Hence, this study aimed to measure RBP4, LCN2 and hsCRP levels in individuals with IFG, IGT, and newly diagnosed T2DM and to examine their relationship with insulin resistance and inflammation." (PMID 40951890, 2025). "To investigate whether LCN2 deletion inhibits insulin resistance, we used HFD/STZ-induced diabetic WT and LCN2 KO mice." (PMID 35884685, 2022).
Insulin resistance (continued). "Since NAFLD seems to be associated with classical indicators of metabolic syndrome (e.g., insulin resistance, Type 2 diabetes, and dyslipidemia), it is no wonder that LCN2 overexpression was lately defined as a hepatic manifestation of a metabolic syndrome." (PMID 33799862, 2021). "Another study, done on Chinese subjects, proved that LCN2 serum levels are elevated in patients with NAFLD as opposed to the control and that they highly correlate with both inflammation (C-reactive protein) and insulin resistance." (PMID 33799862, 2021). "In this study, we did not observe any relationship between lipocalin-2 and adiposity or insulin resistance at baseline." (PMID 24205333, 2013). "In another study as well, prominent expression of the LCN2 protein was found in the visceral adipocytes of obese patients (with insulin resistance and elevated high-sensitivity CRP but without apparent liver injury)." (PMID 23875831, 2013). "Furthermore, another adipokine recently identified with a key role in insulin resistance is LCN-2, as demonstrated in LCN-2 knockout mice." (PMID 20671929, 2010). "Also, there is a close correlation between BMI, waist circumference, fat percentage, triglyceride, homeostatic model assessment–insulin resistance (HOMA–IR) and lipocalin-2 (LCN2), as increased serum levels of LCN2 have been found in obese adolescents and in adult patients." (PMID 39683642, 2024). "However, we also observed no change in PAI-1 or lipocalin-2 in response to overfeeding and insulin resistance." (PMID 24205333, 2013). "Although we found that ABE improves insulin resistance and hepatic steatosis in HFD-fed mice, we did not directly elucidate the role of LCN2 in inflammation and oxidative stress." (PMID 36501079, 2022).
colitis (116 papers, 2008 to 2025). Inflammation of the colon. "The correlation of albuminuria, Lcn2, and Il‐1β expression with colitis markers strengthens the implication of causality between a gut‐barrier defect and kidney inflammation in this model." (PMID 40018982, 2025). "Consistent with body weight loss, the fecal level of lipocalin-2, an inflammatory marker of colitis, was significantly elevated in sorbitol-treated mice on day 8 post-DSS treatment." (PMID 40678521, 2025). "Prophylactic N5 administration alleviated colitis symptoms (weight loss, colon shortening), reduced fecal and serum lipocalin-2 levels, and suppressed colonic pro-inflammatory cytokines (IL-1β, IL-6)." (PMID 40813467, 2025). "To further confirm the induction of colitis, we measured the levels of fecal lipocalin-2 (Lcn-2), also known as a neutrophil gelatinase-associated lipocalin (NGAL), a biomarker of intestinal inflammation." (PMID 41377969, 2025). "Genes such as C3, Ccl2, Cxcl1, Ifi44, Lcn2, S100a8, and Tnf were strongly induced during colitis, mirroring previously reported inflammation-associated transcriptional responses." (PMID 40806068, 2025). "Collectively, these findings suggest that LCN2 governed the functionality of ILC3s and their susceptibility to ferroptosis in colitis." (PMID 39300068, 2024). "Since the Hnf4aΔIEC mice we included in this longitudinal analysis all showed histopathologic features of colitis by 52 wk, we tested if any microbial taxa were associated with episodically elevated fecal Lcn2 using two different methods." (PMID 37526424, 2023). "The differences in colitis corresponded with markedly reduced colonic expression of genes encoding the proinflammatory molecules IL-6 and Lcn2 in the CTB-Ent group compared to CTB control mice." (PMID 36094114, 2022). "In IL10KO mice, MDX supplementation caused an increase in colitis incidence and earlier disease onset as assessed by fecal LCN2 levels." (PMID 35359925, 2022). "In contrast, Lcn-2 deficiency can protect mice from dextran sodium sulfate and Salmonella Typhimurium-induced colitis, suggesting a pathogenic role of Lcn-2 in colitis." (PMID 36341389, 2022). "Previous studies focused mainly on the mucosal Lcn2 expression during colitis-associated intestinal inflammation." (PMID 34572499, 2021). "In the ank/ank mouse model, the discovery of elevated Lcn2 associated with subclinical colonic inflammation and ankylosis is a novel serological feature linking the gut-joint entities." (PMID 32188494, 2020). "To identify bacteria associated with colitis, we determined the most dominant bacteria that are associated with increased fecal Lcn2 levels by Spearman ranking correlation analysis." (PMID 33027280, 2020). "Inflammation-associated induction of LCN2 appears to be protective against pathology because Lcn2 deficient mice are sensitized to developing colitis." (PMID 30398151, 2018). "Twenty-eight genes exhibited overlap between both datasets, which included Lcn2 and Lrg1, pro-inflammatory genes previously implicated in colitis." (PMID 30455703, 2018). "As expected colitis caused an increase of fecal lipocalin-2 in “colitis” and in “arthritis + colitis” groups." (PMID 28926599, 2017). "In the present article, we monitored dextran sodium sulfate (DSS)-induced colitis development upon Lipocalin 2 (Lcn2) neutralization, and examined the survival of Lcn2 deficient (Lcn2KO) mice and their WT littermates upon DSS challenge." (PMID 27500193, 2016). "The findings of the present study revealed that Lcn2 prevents the development of spontaneous colitis in IL-10 deficient mice by enhancing phagocytic bacterial clearance in macrophages." (PMID 27734904, 2016). "Similarly, another polyol, mannitol, was found to exacerbate DSS-induced colitis, as evidenced by increased weight loss and elevated fecal levels of lipocalin-2." (PMID 40678521, 2025).
colitis (continued). "Importantly, gene expression levels of Lcn2, a biomarker of intestinal inflammation released by immune cells, and Il1b, the potent pro-inflammatory cytokine induced during colitis, were highly affected by MCJ deficiency when mice were treated with DSS." (PMID 35705557, 2022). "To determine the role of these bacterial species in colitis, we isolated E. coli as the most abundant bacteria associated with increased Lcn2 levels in the intestine, and determined full genomic sequences of four independent E. coli isolates, NI1429, NI1413, NI1423 and NI1522." (PMID 33027280, 2020). "Finally, in mice deficient in IL-10 and the antimicrobial peptide Lipocalin-2, Alistipes was shown to flourish and was sufficient to induce colitis and tumorigenesis in IL-10 deficient mice." (PMID 28713378, 2017). "In conclusion, Lcn2 prevented the development of spontaneous colitis in IL-10 deficient mice." (PMID 27734904, 2016). "In addition, fecal Lcn-2 marks the severity of spontaneous colitis development in IL-10 deficient mice." (PMID 22957064, 2012). "Therefore, LCN2 was assumed to be a bacterially-induced protein playing important roles in maintaining gut homeostasis, thereby reducing the susceptibility to develop colitis." (PMID 34884961, 2021). "Lcn2 is known to play an inflammatory role in colitis through mediating intestinal epithelial cell pyroptosis." (PMID 40356657, 2025). "The strongest negative correlations were observed between the histopathological scoring of the colitis and kidney weight, as well as between the colon length and the kidney Lcn2 transcription." (PMID 40018982, 2025). "The severity of the colitis correlated with the appearance of kidney injury markers including albuminuria, and increased mRNA expression of Lcn2 and Kim‐1." (PMID 40018982, 2025). "Kidney transcription of Lcn2, a highly sensitive tissue damage marker, was strongly elevated by colitis." (PMID 40018982, 2025). "Specifically, it was shown that induction of colitis is accompanied by upregulation of lipocalin-2 (LCN2) in ILC3s, particularly within the NKp46+ILC3 subpopulation." (PMID 41194916, 2025). "Colitis increased albuminuria, reduced kidney weight, and induced transcription of lipocalin 2, kidney injury molecule‐1, and interleukin‐1beta, as well as increased immunostaining signal of c‐Jun and NF‐κB p65 in the kidneys." (PMID 40018982, 2025). "Our research aimed to investigate the impact of endogenous alterations in LCN2 expression on the regulatory function of ILC3s under normal and colitis-related conditions." (PMID 39300068, 2024). "Transplantation of both human microbiota HM1 and mouse-adapted microbiota IMM-g1 or IMM-g2 to GF 129 Il-10−/− mice induced severe colitis as assessed by colon histology, non-invasive f-LCN2, and inflammatory cytokine levels." (PMID 39113097, 2024). "Specifically, our findings indicate that LCN2 mediated the regulatory effect of ILC3s on colitis through the ATF4-xCT/GPX4 axis." (PMID 39300068, 2024). "Neutrophils constitutively express lipocalin-2 and increased fecal levels have been proposed as a sensitive marker of gut dysbiosis and intestinal inflammation in mouse models of colitis." (PMID 38404579, 2024). "Further, the correlation between biological gases and colitis phenotypes, including changes in body weight and faecal LCN2 levels, were analysed." (PMID 39290658, 2024). "The hydrogen (H2) level was found to be negatively correlated with the level of lipocalin-2 (LCN2), a gut inflammation biomarker, and weight loss due to DSS-induced colitis." (PMID 39290658, 2024). "Specifically, differential expressed genes (DEGs) related to colitis such as Mmp10, Tnfaip3, Lcn2, Serpine1, and Pla2g4f were upregulated in the colon tissue of colitis mice in DVF group." (PMID 38172943, 2024).
colitis (continued). "In this study, mouse models were used to continuously measure biogas components that were correlated to body weight, LCN2 levels, and gut microbiota composition from the onset to the symptom resolution of experimental colitis." (PMID 39290658, 2024). "Previous research has demonstrated associations between A. muciniphila growth, lipocalin-2, and weight loss in DSS-induced colitis, and limited anti-inflammatory activity in IL-10 -/- models." (PMID 39683625, 2024). "Herein, we substantiated the specific regulatory effect of LCN2 on mouse colitis through the inhibition of ILC3 ferroptosis and promotion of ILC3 functionality." (PMID 39300068, 2024). "In this study, changes in five low-molecular-weight biogases, weight loss, faecal LCN2 levels, and gut microbiota composition during DSS-induced colitis were measured, and H2 level was found to have the strongest correlation with colitis outcomes." (PMID 39290658, 2024). "Fecal miRNAs of host origin were analyzed before and during colitis as attested by levels of fecal lipocalin-2, a dynamic marker of intestinal inflammation." (PMID 39224018, 2024). "Our data for disease activity index, colonic lipocalin-2 levels, and claudin-4 immunoreactivity showed an effective colitis-like pathophysiology in both the wild type and AppNL-G-F mice." (PMID 37511312, 2023). "The elevated levels of fecal Lcn2, which serves as a broadly dynamic marker of gut inflammation was also found in the colitis mice." (PMID 37774039, 2023). "The measurement of fecal lipocalin-2, known as a dynamic marker of inflammation mainly secreted by neutrophils, was used as a non-invasive method to confirm the development of colitis in all the mice over time." (PMID 37373511, 2023). "Using antibiotic depletion and gnotobiotic approaches, we show that episodically elevated fecal Lcn2, episodic loose stools, and histopathological features of colitis are all microbiota dependent in this model." (PMID 37526424, 2023). "Lcn2, a member of the lipocalin family, is one of the widely used disease activity markers for colitis." (PMID 37489647, 2023). "Analysis of the fecal biomarker lipocalin 2 over time showed a suppression trend of colitis in hCA I over the other groups." (PMID 36289244, 2022). "LFD 2% male mice had higher expression of Acod1, Lcn2, and S100a9, which are upregulated in colitis and inflammatory bowel disease." (PMID 36501176, 2022). "In this study, exposure to proteolytic supernatant in a DSS-induced model of colitis accelerated the manifestation of inflammation symptoms and led to an increase in lipocalin-2 levels." (PMID 36445085, 2022). "Animals colonized with H. hepaticus developed colitis, as indicated by a significant increase in fecal lipocalin-2 concentrations relative to control mice 2 weeks after inoculation with H. hepaticus (day −21)." (PMID 35900107, 2022). "Though S100A9 and Lcn2 are upregulated in colitis, this is the first study to observe evidence of these proteins in the brain of mice with colitis." (PMID 34983592, 2022). "IL-10 and LCN2 double-knockout mice have more severe colitis and a higher expression of inflammatory factors." (PMID 36591221, 2022). "In our study, anti-siderophore antibodies conferred protection from AIEC colonization and exacerbation of colitis in both Lcn2−/− and WT (i.e., Lcn2-proficient) mice." (PMID 36094114, 2022). "Among the diverse physiological functions of Lcn2, one is to limit bacterial growth enhancing their efficacy as a treatment for experimental colitis." (PMID 35705557, 2022). "Murine models of colitis have been adapted to relatively mild protocols in order to study the effect of low-grade endotoxemia on LCN2 expression." (PMID 34578967, 2021). "Acute DSS colitis significantly increased expression of Lcn2, Ptprc, Cd8b, and Snca in the colon of male mice and of Lcn2 in female mice." (PMID 34412704, 2021).